PSMA2 (proteasome 20S subunit alpha 2)
Description:
Component of the 20S core proteasome complex involved in the proteolytic degradation of most intracellular proteins. This complex plays numerous essential roles within the cell by associating with different regulatory particles. Associated with two 19S regulatory particles, forms the 26S proteasome and thus participates in the ATP-dependent degradation of ubiquitinated proteins. The 26S proteasome plays a key role in the maintenance of protein homeostasis by removing misfolded or damaged proteins that could impair cellular functions, and by removing proteins whose functions are no longer required. Associated with the PA200 or PA28, the 20S proteasome mediates ubiquitin-independent protein degradation. This type of proteolysis is required in several pathways including spermatogenesis (20S-PA200 complex) or generation of a subset of MHC class I-presented antigenic peptides (20S-PA28 complex).
Synonyms: HC3; MU; PMSA2; PSC2
Tractability: Small molecule: an approved drug acts on it; a structure with a bound ligand is known; a high-quality ligand is known; it belongs to a druggable protein family. Antibody: its Gene Ontology location is reachable by antibodies, with high confidence. PROTAC: ubiquitination databases record sites on it; its protein half-life has been measured; a small molecule that binds it is known.
Gene: Protein-coding gene on chromosome 7 (42,916,828 to 42,932,223, reverse strand). Ensembl gene ENSG00000106588.
Subcellular location: Cytoplasm; Nucleus
Pathways (Reactome):
Immune System: AMPK-induced ERAD and lysosome mediated degradation of PD-L1(CD274); Activation of NF-kappaB in B cells; Antigen processing: Ub, ATP-independent proteasomal degradation; Antigen processing: Ubiquitination & Proteasome degradation; CLEC7A (Dectin-1) signaling; Cross-presentation of soluble exogenous antigens (endosomes); Dectin-1 mediated noncanonical NF-kB signaling; Downstream TCR signaling; ER-Phagosome pathway; FCERI mediated NF-kB activation; GSK3B-mediated proteasomal degradation of PD-L1(CD274); Interleukin-1 signaling; NIK-->noncanonical NF-kB signaling; Neutrophil degranulation; SPOP-mediated proteasomal degradation of PD-L1(CD274); TNFR2 non-canonical NF-kB pathway
Cell Cycle: APC/C:Cdc20 mediated degradation of Securin; APC/C:Cdh1 mediated degradation of Cdc20 and other APC/C:Cdh1 targeted proteins in late mitosis/early G1; Autodegradation of Cdh1 by Cdh1:APC/C; Autodegradation of the E3 ubiquitin ligase COP1; Cdc20:Phospho-APC/C mediated degradation of Cyclin A; FBXL7 down-regulates AURKA during mitotic entry and in early mitosis; G2/M Checkpoints; SCF(Skp2)-mediated degradation of p27/p21; SCF-beta-TrCP mediated degradation of Emi1; Separation of Sister Chromatids; The role of GTSE1 in G2/M progression after G2 checkpoint; Ubiquitin-Mediated Degradation of Phosphorylated Cdc25A; Ubiquitin-dependent degradation of Cyclin D
Signal Transduction: Asymmetric localization of PCP proteins; Degradation of AXIN; Degradation of DVL; Degradation of GLI1 by the proteasome; Degradation of GLI2 by the proteasome; Degradation of beta-catenin by the destruction complex; GLI3 is processed to GLI3R by the proteasome; Hedgehog 'on' state; Hedgehog ligand biogenesis; MAPK6/MAPK4 signaling; Negative regulation of NOTCH4 signaling
and 29 more pathways
Gene Ontology:
Molecular function: protein binding; structural constituent of proteasome
Biological process: proteasomal protein catabolic process; proteasome-mediated ubiquitin-dependent protein catabolic process; regulation of proteasomal protein catabolic process; response to oxidative stress; response to virus; apoptotic process; CD8-positive, alpha-beta T cell differentiation; CD8-positive, alpha-beta T cell homeostasis; cellular response to type I interferon; DNA damage response; DNA repair; flagellated sperm motility; immune system process; meiotic cell cycle; negative regulation of regulatory T cell differentiation; positive regulation of interleukin-2 production; positive regulation of tumor necrosis factor production; positive regulation of type II interferon production; proteasomal ubiquitin-independent protein catabolic process; regulation of G1/S transition of mitotic cell cycle; response to type II interferon; spermatogenesis; T-helper 1 cell differentiation; T-helper 17 cell differentiation; thymic T cell selection; and 2 more
Cellular component: cytoplasm; extracellular exosome; nucleus; proteasome complex; proteasome core complex; cytosol; extracellular region; ficolin-1-rich granule lumen; nucleoplasm; P-body; proteasome core complex, alpha-subunit complex; proteasome storage granule; secretory granule lumen; spermatoproteasome complex; synaptic vesicle
Genetic constraint (gnomAD): Loss-of-function variants: 2 observed, 25.96 expected, observed/expected ratio (o/e) 0.077, 90% interval 0.03 to 0.24. The upper end of that interval is the gene's LOEUF score, 0.24, which puts it in group 1 of 6, group 1 being the genes least tolerant of losing a copy. Missense variants: 113 observed, 232.51 expected, observed/expected ratio (o/e) 0.49, 90% interval 0.42 to 0.57. Synonymous variants: 87 observed, 88.52 expected, observed/expected ratio (o/e) 0.98, 90% interval 0.82 to 1.17.
Homologues: Orthologues: chimpanzee PSMA2 (100% identical), dog PSMA2 (100% identical), guinea pig PSMA2 (100% identical), macaque PSMA2 (100% identical), rabbit PSMA2 (100% identical), mouse Psma2 (99% identical), pig PSMA2 (96% identical), tropical clawed frog psma2 (96% identical), zebrafish psma2a (95% identical), zebrafish psma2b (95% identical), rat Psma2 (94% identical), Drosophila melanogaster Prosalpha2 (78% identical), and 1 more. Paralogues in human: PSMA8 (40% identical), PSMA4 (38% identical), PSMA7 (38% identical), PSMA6 (36% identical), PSMA1 (32% identical), PSMA5 (32% identical), PSMA3 (30% identical), PSMB5 (22% identical), PSMB8 (21% identical), PSMB11 (17% identical), PSMB7 (17% identical), PSMB10 (17% identical), and 6 more.